TNF (tumor necrosis factor)
Diseases named in the same sentence as TNF in open-access papers (continued):
Sharing a sentence is not in itself a finding about the gene and the disease.
Sepsis (continued). "Experimental sepsis led to a systemic cytokine storm resulting in the formation of excessive amounts of both pro-inflammatory cytokines (TNF-α, IL-1β, IL-17 and IL-6) and the anti-inflammatory cytokine IL-10." (PMID 35178052, 2022). "In preliminary studies we found using a more appropriate model for sepsis, i.e., mouse cecal ligation and puncture, that human eMSC reduced levels of IL-6 and TNF-α in sera after 16 h treatments with eMSC (unpublished observation MG, SB, MK)." (PMID 36551231, 2022). "An activation by sepsis factors (LPS, TNF-α, or miR370-3p transfection) damaged mitochondria (fluorescent color staining) and reduced cell ATP, possibly through profound mitochondrial activity (extracellular flux analysis) that was attenuated by BAM15." (PMID 35628259, 2022). "The cytokines production leads to cascades of effects in the onset of sepsis, including pro-inflammatory factors such as TNF-α, IL-1β, and IL-6." (PMID 35510354, 2022). "Compared with sepsis group, levels of TNF-α in sepsis+SO2 group also showed an decreasing trend (p = 0.236, p = 0.040, respectively)." (PMID 35265263, 2022). "The present study confirmed enhanced TNF-α, IL-1β, and miR-103a-3p expressions in sepsis-induced AKI." (PMID 35510354, 2022). "Sepsis is comprised of two phases, hyper-inflammatory phase featured by dramatic elevation of potent cytokines such as TNF-α and IL-6, and immunosuppression phase where inflammatory cytokines decrease significantly." (PMID 35167625, 2022). "Activation of this axis promotes increased expression/secretion of pro-inflammatory cytokines such as TNF-α, IL-6, IL-1β and IL-17, which in turn contribute to the cytokine storm and multiple organ failure (MOF) associated with sepsis." (PMID 36119089, 2022). "GC is also produced endogenously in sepsis patients in whom cytokines like IL-1β, TNFα, and IL-6 induce its production from the adrenal cortex using cholesterol as a substrate to reduce inflammatory responses." (PMID 36443794, 2022). "Another approach investigated blockade of TNFα to blunt the inflammatory response in sepsis patients." (PMID 35634305, 2022). "Levels of TNF-α in plasma and lung tissues in control group, sepsis group, sepsis+SO2 group, and SO2 group were 43.8 ± 2.94 pg/mL, 52.2 ± 7.50 pg/mL, 47.6 ± 4.59 pg/mL, and 50.8 ± 10.60 pg/mL, respectively." (PMID 35265263, 2022). "During sepsis, miRNAs were observed to be mainly involved in the activation of TLR-4, leading to the production of pro-inflammatory cytokines (IL-6, IL-1, TNF) that cause endothelial dysfunction and organ damage." (PMID 36012630, 2022). "Giving that changes in inflammatory factors, including TNF‐α, IL‐1β, IL‐6, IL‐10, and iNOS, are a major characteristic of the sepsis model, we measured the inflammatory cytokines after LPS treatment." (PMID 35474613, 2022). "BAFF significantly promotes the secretion of serum IL-1β, TNF-α, IL-6 and other inflammatory factors in the LPS-induced sepsis model whereas neutralization of BAFF markedly inhibits pro-inflammatory factor release." (PMID 35320937, 2022). "Second, LPS activates inflammatory cells to secrete TNF-a, IL-1β, IL-6 and other cytokines, which mediate the development of sepsis." (PMID 35664882, 2022). "Inflammatory factors such as IL-6 and TNF-a and oxidative stress indicators such as SOD can be used as early diagnostic markers for AKI caused by sepsis, and these markers have important values for judging the prognosis of the disease." (PMID 35611245, 2022). "The crucial role of TNF-α in sepsis is well-established, as abundant data in this regard have been previously reported." (PMID 35337084, 2022). "Hyperferritinemia is also related to a pro-inflammatory state in sepsis, with increases of interleukin (IL)-6, IL-18, Interferon γ, sCD163 and a decrease of the IL-10/tumor necrosis factor α ratio as quantitative markers of inflammation." (PMID 36614993, 2022).
Sepsis (continued). "Sham-operated feces recipients showed a higher 5-day survival rate and a lower level of proinflammatory cytokines (IL-1β, P < 0.001; TNF-α, P = 0.001) than saline-treated feces recipients, indicating that sepsis-induced gut dysbiosis exacerbates sepsis." (PMID 35658593, 2022). "RT–PCR: reverse transcription polymerase chain reaction; SC: sham-operated; SCFA: short-chain fatty acid; SLI: sepsis-related liver injury; TNF-α: tumour necrosis factor-alpha; cxcl/ccl: chemokine [C–C motif] ligand." (PMID 35191819, 2022). "The kinetics of TNFα’s appearance in the liver vary considerably between the experimental models of sepsis used and have led to mixed conclusions regarding the role of cell signaling as a mechanism of regulating oxidative phosphorylation." (PMID 35626633, 2022). "In a rat model of polymicrobial sepsis, β-glucan treatment attenuated proinflammatory cytokines TNF-α and IL-6 while increasing anti-inflammatory cytokine IL-10 concentrations." (PMID 35833122, 2022). "TNF-α seems to be the first cytokine released when systemic inflammation is observed and shows high levels within several hours after the onset of sepsis, followed by IL-1 and then IL-6." (PMID 35106183, 2022). "In a separate model of sepsis, serum levels of TNF-α and nitrite were significantly decreased in a dose-dependent manner with increasing doses of DIE." (PMID 35607518, 2022). "Most notably, oxytocin abolishes the sepsis-induced increase in TNF-α and thereby protects against sepsis-related, cytokine-mediated damage to multiple organs." (PMID 35572539, 2022). "In sepsis, increased levels of TNF-α activate the external apoptotic pathways, which involves the activation of death receptors." (PMID 35814769, 2022). "Sepsis leads to systemic inflammatory responses and increased levels of the pro-inflammatory cytokine, such as the tumor necrosis factor α (TNF-α), interleukin (IL)-1β, IL-6, and IL-8 resulting in diffuse alveolar epithelial-endothelial barrier damage." (PMID 35812413, 2022). "Like MAMP, AGEs can directly activate the TLR2/4 signaling pathway in various cells and stimulate the production of proinflammatory cytokines such as IL-6 and TNF-α to take part in the pathogenesis of sepsis." (PMID 35719361, 2022). "Blocking the Tim-3 signaling pathway significantly increased TNF-α levels in the supernatant of T lymphocytes of patients with sepsis." (PMID 36303229, 2022). "Our study is the first to demonstrate that inhibiting S100A12 with neutralizing anti-S100A12 human antibody significantly increased TNF-α and IL-10 production in LPS-stimulated PBMCs from controls and patients with sepsis." (PMID 35723375, 2022). "The pathogenesis of sepsis mainly lies in the massive release of inflammatory mediators such as tumor necrosis factor (TNF-α), interleukin (IL), platelet-activating factor (PAF), etc., caused by infection." (PMID 35783411, 2022). "Administering SOD – gliadin extract of Cucumis melo L.C. gliadin significantly reduced TNF-α levels in sepsis-induced rats, with p < 0.001." (PMID 36082333, 2022). "To determine if gestational sepsis induces upregulation of cytokine up in neonates, we analyzed the levels of TNF-α, IL-1β, and IL-6 in the liver, lung, and brain of neonates at P2 and P8." (PMID 33632243, 2021). "As a late inflammatory mediator, HMGB1 can be induced by LPS and it participates in pyroptosis during the pathogenesis of sepsis via the secretion of pro-inflammatory factors, such as TNF-α, IL-1, II-6, and IL-8." (PMID 33714207, 2021). "The modulation of TNFα and other inflammatory cytokines and chemokines is considered important in the treatment of severe infectious diseases, especially sepsis or septic shock." (PMID 34921186, 2021). "The best combination of cytokines to distinguish FMF from sepsis was found to be GM-CSF and TNF-α, with high accuracy observed (sensitivity 93%, specificity 94%, and accuracy 93%)." (PMID 34654467, 2021).
Sepsis (continued). "We measured the pro-inflammatory cytokine levels (IL-1β, IL-6, TNF-α) in the plasma and hippocampus to evaluate central and peripheral inflammation during the acute phase of sepsis in SAMP8 and SAMR1." (PMID 33643027, 2021). "Recent studies using tumor necrosis factor-alpha (TNF-alpha), neutrophil CD64, or toll-like receptors (TLR) as early diagnostic markers have added little to the armamentarium of sepsis diagnosis." (PMID 34441323, 2021). "This study suggested that berberine, chlorogenic acid, jarrorhizine, palmatine, evodin, and evodiamine had inhibitory effects on sepsis-induced inflammatory response, especially the TNF-α." (PMID 33506010, 2021). "We focused principally on monocyte TNFα production because of its crucial role in the inflammatory cascade and data linking reduced monocyte TNFα release to survival following sepsis, although a similar pattern was observed with IL6." (PMID 34825153, 2021). "Our results suggest that PEGylated catalase can effectively regulate cytokine production by activated leukocytes, suppress the elevated level of AST, ALT, TNF-α, and IL-6 in mice with induced sepsis, and significantly improve the survival rate of the mice." (PMID 34888304, 2021). "In sepsis, lipopolysaccharide (LPS) and inflammatory cytokines, such as TNF-α, IL-1β, IL-6, and IL-17, can regulate the level of G-CSF." (PMID 34795984, 2021). "PGN and LTA, cell wall components of S. aureus, can also interact with CD14 molecules through TLR2 and stimulate the release of proinflammatory cytokines (TNF-α and IL-6) and chemokines (IL-8) further potentiating the systemic inflammation in sepsis." (PMID 33546401, 2021). "Studies have found that TNF-α and IL-1β are the main mediators of cardiac insufficiency in sepsis and are considered to be direct myocardial depressants." (PMID 34950238, 2021). "For example, lnc‐KCNQ1OT1 negatively regulates inflammatory factors (including TNF‐α, IL‐1β, and IL‐6) in sepsis‐induced myocardial injury and intimal hyperplasia." (PMID 34761437, 2021). "The present study found that inhibition of mitochondrial division alleviated sepsis-induced inflammation, including the release of cytokines TNFα and IL-6, and the phosphorylation of NF-κB." (PMID 34566637, 2021). "Ulinastatin, a human protease inhibitor and androstenediol, a metabolite of dihydroxystheniandrosterone, reduce plasma levels of TNF-α and IL-6 in rats with sepsis." (PMID 34577795, 2021). "Accumulating studies have well documented that macrophages play an important role in sepsis as it is one of the major sources of tumor necrosis factor-a (TNF-a) and interleukin-6 (IL-6)." (PMID 33536546, 2021). "TNF-a can be detected in the serum of many patients with sepsis and its concentrations are correlated with both severity and prognosis." (PMID 33917002, 2021). "Macrophage-mediated inflammation releases cytokines such as TNF-α, IL-1β, IL-6, and IL-8, which play an important role in the pathogenesis of sepsis." (PMID 34220338, 2021). "The increase in plasma levels of inflammatory cytokines, such as IL-6 or TNF-α, is proportional to the severity of sepsis, and correlates with mortality." (PMID 33946773, 2021). "The gene expression of inflammatory mediators including IL-6 and TNF-α was also elevated after sepsis." (PMID 33859538, 2021). "LOX-1 deletion in a murine model of polymicrobial sepsis reduced IL-6 and TNFα levels in the blood and lungs, which enhanced bacterial clearance and prevented neutrophil activation." (PMID 34616409, 2021). "Administration of tannic acid reduced the level of TNF-α in testicular tissue compared with the sepsis group (0.79 ± 0.02 vs 1.53 ± 0.02 %, P<0.05)." (PMID 35317115, 2021). "TNF-α, IL-6, and IL-1β are all important proinflammatory factors, which play an important role in the occurrence and development of sepsis." (PMID 34721636, 2021).
Sepsis (continued). "Tumor necrosis factor alpha, IL-6, and IL-1β are significant pro-inflammatory factors, which can lead to and promote the occurrence and development of sepsis." (PMID 34616305, 2021). "In the hyperinflammation model of cecal slurry model in rats (6 h after sepsis induction), mitochondrial transplantation attenuated inflammation, as shown by reduced TNF-α levels in the spleen." (PMID 33413559, 2021). "In severe sepsis, however, several proinflammatory cytokines (including IL-1, IL-6 and TNF-α), induced by endotoxins, lipopolysaccharides and other infectious mediators, promote the generation and release of procoagulant tissue factor of endothelial cells." (PMID 33654698, 2021). "The proinflammatory response in the acute phase of sepsis eliminates invading pathogens and involves immunocyte activation and subsequent production of cytokines such as TNF-α, IL-1β, and IL-6." (PMID 34907156, 2021). "The statistical analysis indicated that, compared with those in the sham group, IL-1β, TNFα, IL-6, and IFNγ levels in the Sepsis group were upregulated, while SOD and GSH-PX levels were downregulated." (PMID 34489703, 2021). "Our data showed a highly significant difference regarding genotype and allelic distribution of TNF−α (–376 G/A) rs1800750 among all the studied groups: acute septic shock, sepsis, and control subjects (p < 0.001)." (PMID 34692772, 2021). "In a sepsis model, pioglitazone reduced LPS-induced TNFα and IL-6 production from mouse macrophages through inhibition of NFκB." (PMID 34831270, 2021). "For example, during exercise, interleukin (IL)-6 and IL-15 are secreted by muscle in a pulsatile fashion and, in contrast to sepsis or inflammation, independent from tumor necrosis factor (TNF)-α secretion." (PMID 34246305, 2021). "In a zinc supplementation RCT of neonates with clinical sepsis in India, zinc supplementation was found to reduce concentrations of serum TNF-α and IL-6." (PMID 34836049, 2021). "Among the cytokines, TNF-α levels were significantly higher in patients who worsened than in those who improved in the trauma/surgery and sepsis patient groups with sufficient and poor predictive value, respectively." (PMID 33917002, 2021). "Three recombinant humanized anti-MV-A iNOS mAbs—rHA mAb, rHD mAb, and rHJ mAb—were found to rescue mice from a lethal challenge in three different mouse models of sepsis: an LPS model, a TNFα model, and our in-house MV-A iNOS model of sepsis." (PMID 34948167, 2021). "PEGylated catalase can effectively regulate the cytokine production by activated leukocytes, suppress the elevated level of AST, ALT, TNF-α, and IL-6 in mice with induced sepsis, and significantly improve the survival rate." (PMID 34888304, 2021). "TNF-α is a potent inducer of inflammatory response and a key regulator of innate immunity in sepsis-related ALI, which is often used to activate neutrophils." (PMID 34641966, 2021). "Sepsis patients exhibited significantly higher expression and production of NLRP3 and the proinflammatory cytokines (TNF-α, IL-6 and IL-1β) than healthy controls, and these levels were significantly increased with sepsis progression." (PMID 34172780, 2021). "We also observed that TNF-Exo resulted in a significant lung inflammatory response, suggesting that exosomes released from TNF-α-activated PMNs are a kind of pro-inflammatory exosomes and play an important role in sepsis-related ALI." (PMID 34641966, 2021). "Historically, direct anti-hyperinflammatory strategies that attempt to block cytokines, such as interleukin-1 (IL-1) and tumor necrosis factor (TNF), have been the main therapeutic pathway against sepsis." (PMID 34677433, 2021). "JMJD3 demonstrates promoting properties in sepsis by upregulating pro-inflammatory cytokines, IL-1β, and TNF-α expression." (PMID 33413595, 2021). "In sepsis, EC activation induced adhesion receptors and released inflammatory mediators, such as interleukin (IL)-1, IL-6 and tumor necrosis factor." (PMID 33482737, 2021).
Sepsis (continued). "IgM levels did not correlate with albumin (r = 0.058, p = 0.73), or immune markers TNFα (r = −0.027, p = 0.86), IL-1 (r = 0.1292, p = 0.91), IL-6 (r = −0.1615, p = 0.30), or IL-8 (r = −0.0209, p = 0.89) in the sepsis cohort." (PMID 34830673, 2021). "Cytokine secretion mediates brain dysfunction, and the increases of IL-1β, IL-6, and TNF-α are involved in cognitive impairment after sepsis." (PMID 35111693, 2021). "Endogenous TNF-α or TNF receptors present in the disease microenvironment have been shown to play a key role in MSC efficacy in pre-clinical models of sepsis and cardiomyopathy." (PMID 34831203, 2021). "Since an imbalance between the pro- and anti-inflammatory systems is considered to be a vital mechanism of sepsis, we measured the levels of pro-inflammatory cytokines including IL-6, TNF-α, and HMGB1 in the kidneys." (PMID 33936050, 2021). "During the subacute (3-day and 5-day sepsis groups) and prolonged phase (7-day sepsis group), pituitary TNF-α mRNA levels were similar to those of healthy control mice." (PMID 33593393, 2021). "In the animal sepsis model, the expression levels of inflammatory factors, such as TNF-α, IL-1, and IL-6, are significantly elevated in brain tissues, accompanied by the increased cerebral water content and brain permeability to blood dyes." (PMID 34592907, 2021). "In the immune paralysis model (24 h after sepsis induction), mitochondrial transplantation significantly increased TNF-α production in ex vivo splenocytes stimulated with LPS." (PMID 33413559, 2021). "Previous studies have reported that the levels of cytokines such as IL-1, IL-6, IFN-γ, and TNF-α increase during sepsis as an immune response to infection." (PMID 34070883, 2021). "AKI in sepsis is accompanied by systemic inflammation and the excessive production of pro-inflammatory cytokines including TNF-α, IL-6, and IL-1β." (PMID 33841147, 2021). "In the Se groups, plasma TNF‐α concentration was increased in T2 sepsis (106.2 ± 905.5 pg/ml) compared to T0 (0 ± 31.3 pg/ml) and T1 sepsis (0 ± 94.1 pg/ml)." (PMID 34288548, 2021). "Taken together, TNF-α and IFN-γ work together to cause the cytokine storm and cell death linked to COVID-19 and sepsis." (PMID 34946543, 2021). "EX-527, a Sirt1 inhibitor restored myeloid cell IL1B and TNF production when administered after sepsis." (PMID 34163486, 2021). "The overproduction and release of cytotoxic molecules, such as interleukin (IL)-1, IL-17 and tumor necrosis factor (TNF), which constitute the cytokine storm, are likely responsible for the excessive systemic inflammation associated with sepsis." (PMID 34712743, 2021). "More importantly, suppression of NF-κB contributed to a reduction of release of LPS-induced pro-inflammatory cytokines such as TNF-α, IL-1β, and IL-6 in sepsis." (PMID 33413595, 2021). "Our results showed that sepsis increased the production of inflammatory cytokines TNF-α, IL-2 and IFN-γ, which was ameliorated by pretreatment with L. rhamnosus TR08." (PMID 34536996, 2021). "Its derivative, protocatechuic acid isopropyl ester, had been proved to protect murine model against sepsis by inhibiting TNF-α production, NO production, and the augmentation of IL-6 and IL-10." (PMID 34938184, 2021). "Previous study has found that HT can inhibit the expression of inflammatory factors such as TNF-α, IL-1β and IL-6, and attenuate infiltration of activated immune cells in LPS-mediated sepsis in mice." (PMID 34858184, 2021). "Another analysis of over 1,400 pneumonia patients in the United States reported that IL-6, tumor necrosis factor (TNF), and IL-10 were elevated at intake in patients who developed severe sepsis and/or ultimately died." (PMID 33594340, 2021). "We found that among sepsis-associated inflammatory cytokines (e.g., IL-1β, IFN-γ, TNF-α and G-CSF) and LPS, G-CSF and IFN-γ were found to significantly reduce DC development and functional differentiation." (PMID 34566996, 2021).